LINC01606 (long independently transcribed non-coding RNA 1606)
Synonyms: TCONS_l2_00027778
Gene: Long non-coding RNA gene on chromosome 8 (57,142,643 to 57,244,793, forward strand). Ensembl gene ENSG00000253301.
Diseases named in the same sentence as LINC01606 in open-access papers:
LINC01606 is named in the same sentence as 6 diseases in open-access papers, as found by Europe PMC text mining. Sharing a sentence is not in itself a finding about the gene and the disease. The quoted sentences say what the papers report.
colon cancer (3 papers, 2022 to 2024). "LINC01606 acts as an oncogene promoting colon cancer cell invasion in vitro and in vivo, and is associated with the Wnt/β-catenin signaling pathway." (PMID 39026978, 2024). "LINC01606 acts as an oncogene and promotes the stemness of colon cancer cells both in vitro and in vivo." (PMID 39026978, 2024). "LINC01606 functioned as an oncogene and promotes colon cancer cell growth,invasion and stemness both in vitro and in vivo." (PMID 35485210, 2022). "Thus, these analyses of the LINC01606 level and prognostic or diagnostic value in cancer specimens indicated that high expression of LINC01606 might play an oncogenic role and predict a poor prognosis in colon cancer." (PMID 35485210, 2022). "In contrast, activation of LINC01606–Wnt/β‐catenin axis signalling led to resistance of colon cancer cells to the ferroptosis inducer RSL3 by BML‐284 treatment of SW480 and HT29 cells." (PMID 35485210, 2022). "LINC01606 functions as an oncogene to facilitate tumor cell stemness, proliferation and inhibit ferroptosis and is a promising therapeutic target for colon cancer." (PMID 35485210, 2022). "To investigate the biological function of LINC01606 in colon cancer cells, we generated SW480 and HT29 clones that had either stable knockdown of LINC01606 by shRNALINC01606 or stable overexpression of LINC01606 transcript by lentivirus." (PMID 35485210, 2022). "To determine whether LINC01606 knockdown affected stemness‐related markers in colon cancer cells, we performed shRNA knockdown of LINC01606 and lentivirus overexpression of LINC01606 in SW480 and HT29 cells followed by analysis of established CSC markers." (PMID 35485210, 2022). "Overall, these data suggested that LINC01606–Wnt/β‐catenin axis signalling might promote stemness in colon cancer cells by blocking the process of ferroptosis." (PMID 35485210, 2022). "Subsequently, we found a strong correlation between LINC01606 and SCD1 expression in 83 colon cancer patients, suggesting that LINC01606 might promote SCD1 expression." (PMID 35485210, 2022). "Furthermore, colon cancer patients with higher LINC01606 expression levels also had a shorter OS (p = .047, HR = 1.70) and disease‐free survival (p = .043, HR = 2.0) in GEPIA, further indicating that LINC01606 is most likely a biomarker for colon cancer." (PMID 35485210, 2022). "LINC01606 protects colon cancer cells from ferroptosis by reducing the concentration of iron, lipid ROS, and mitochondrial superoxide, and by increasing mitochondrial membrane potential, while LINC01606 and Wnt/β-catenin form a positive feedback regulatory loop that further inhibits ferroptosis." (PMID 38481525, 2024). "To validate the miR‐423‐5p physical interaction between LINC01606 and the Wnt3a 3′UTR in colon cancer, we primarily performed FISH to confirm the subcellular location of LINC01606 in SW480 and HT29 cells." (PMID 35485210, 2022). "Consequently, LINC01606 might suppress the occurrence of ferroptosis in colon cancer cells." (PMID 35485210, 2022). "To validate whether miR‐423‐5p had a physical interaction with the SCD1 3′UTR in colon cancer, we first detected SCD1 expression following interference or overexpression of LINC01606 and miR‐423‐5p in SW480 and HT29 cells." (PMID 35485210, 2022). "Additionally, colon cancer patients in stage II, III and IV groups had relatively higher expression of LINC01606 than those in the stage I group." (PMID 35485210, 2022).
gastric cancer (3 papers, 2020 to 2021). A primary or metastatic malignant neoplasm involving the stomach. "LINC01606 has been shown to be elevated aberrantly and correlated with metastasis and invasion of gastric cancer, and its expression level is associated with Wnt/β-catenin signaling pathway activation through the regulation of miR-423-5P." (PMID 33317634, 2020). "This suggested that LINC01606 may act as an oncogene in gastric cancer." (PMID 34676164, 2021). "The high expression of LINC01606 in gastric cancer (GC) liberates miR‐423‐5p bound to Wnt3a through a competitive endogenous RNA (ceRNA) mechanism, thereby upregulating Wnt3a expression and inhibiting the Wnt/β‐catenin pathway to promote gastric cancer cell metastasis." (PMID 33174687, 2020).
infertile (1 paper, 2020). "Specifically, the infertility associated CpG module is hypermethylated on chromosome 8 locus in sperm from infertile men, and is located nearby the upstream of LINC01606, a testis-selective long-noncoding RNA gene." (PMID 33317634, 2020).
tumor (2 papers, 2021 to 2022). "LINC01606 expression was substantially upregulated in both tumour spheres compared with adherent cells." (PMID 35485210, 2022). "As expected, the number of spheres formed was significantly inhibited in response to LINC01606 depletion, and conversely, LINC01606 overexpression significantly increased the tumour sphere number." (PMID 35485210, 2022). "The up-regulation of LINC01606 in GC leads to activation of Wnt/β-catenin and promotes the invasion and metastasis of the tumor." (PMID 34094983, 2021). "To validate the potential role of LINC01606 in human colon cCSCs, we detected LINC01606 expression in SW480 and HT29 adherent cells and tumour spheres by qRT‐PCR." (PMID 35485210, 2022).
cancer (1 paper, 2022). A tumor composed of atypical neoplastic, often pleomorphic cells that invade other tissues. "Analysis of RNA‐seq data from TCGA showed that LINC01606 was markedly upregulated in most cancer tissue types compared with normal tissues, such as BRCA, COAD, LUSC, READ and UCEC (p < .05)." (PMID 35485210, 2022). "As expected, the positive percentage of Ki‐67 in cancer tissues with high LINC01606 expression was higher than that in cancer tissues with low LINC01606 expression." (PMID 35485210, 2022). "In summary, this work illustrates that LINC01606 acts as an oncogene to promote cancer cell stemness and inhibit ferroptosis in the positive feed‐forward loop between LINC01606 and Wnt/β‐catenin signalling." (PMID 35485210, 2022). "Furthermore, LINC01606 expression was higher in T4 cancer tissues than in T1 to T3 cancer tissues and in cancer tissues with the positive lymph node metastasis compared with negative lymph node metastasis." (PMID 35485210, 2022). "Notably, LINC01606 and SCD1 were upregulated in colon CSCs, and LINC01606 enhanced the stemness of cancer cells, indicating that LINC01606 might confer ferroptosis resistance ability to colon CSCs." (PMID 35485210, 2022).
LINC01606 also shares sentences with these, for which no sentence is quoted: colorectal cancer (1 paper).